PPP1R16B (protein phosphatase 1 regulatory subunit 16B)
Description:
Regulator of protein phosphatase 1 (PP1) that acts as a positive regulator of pulmonary endothelial cell (EC) barrier function. Involved in the regulation of the PI3K/AKT signaling pathway, angiogenesis and endothelial cell proliferation. Regulates angiogenesis and endothelial cell proliferation through the control of ECE1 dephosphorylation, trafficking and activity (By similarity). Protects the endothelial barrier from lipopolysaccharide (LPS)-induced vascular leakage (By similarity). Involved in the regulation of endothelial cell filopodia extension (By similarity). May be a downstream target for TGF-beta1 signaling cascade in endothelial cells. Involved in PKA-mediated moesin dephosphorylation which is important in EC barrier protection against thrombin stimulation. Promotes the interaction of PPP1CA with RPSA/LAMR1 and in turn facilitates the dephosphorylation of RPSA/LAMR1. Involved in the dephosphorylation of EEF1A1.
Synonyms: ANKRD4; KIAA0823; TIMAP
Tractability: Antibody: UniProt places it where antibodies can reach, with high confidence; its Gene Ontology location is reachable by antibodies, with high confidence; the Human Protein Atlas places it where antibodies can reach. PROTAC: ubiquitination databases record sites on it; its protein half-life has been measured.
Gene: Protein-coding gene on chromosome 20 (38,804,915 to 38,923,025, forward strand). Ensembl gene ENSG00000101445.
Subcellular location: Cell membrane; Nucleus; Cell projection
Subcellular location (Human Protein Atlas): Plasma membrane; Nuclear speckles
Gene Ontology:
Molecular function: protein binding; protein phosphatase regulator activity; enzyme inhibitor activity; myosin phosphatase regulator activity
Biological process: establishment of endothelial barrier; positive regulation of blood vessel endothelial cell proliferation involved in sprouting angiogenesis; positive regulation of endothelial cell proliferation; regulation of phosphatidylinositol 3-kinase/protein kinase B signal transduction; regulation of filopodium assembly; regulation of sprouting angiogenesis
Cellular component: cell projection; nuclear speck; nucleus; perinuclear region of cytoplasm; plasma membrane; cytoplasm
Genetic constraint (gnomAD): Loss-of-function variants: 14 observed, 57.42 expected, observed/expected ratio (o/e) 0.24, 90% interval 0.16 to 0.38. The upper end of that interval is the gene's LOEUF score, 0.38, which puts it in group 1 of 6, group 1 being the genes least tolerant of losing a copy. Missense variants: 547 observed, 760.55 expected, observed/expected ratio (o/e) 0.72, 90% interval 0.67 to 0.77. Synonymous variants: 266 observed, 313.06 expected, observed/expected ratio (o/e) 0.85, 90% interval 0.77 to 0.94.
Homologues: Orthologues: chimpanzee PPP1R16B (99% identical), macaque PPP1R16B (99% identical), pig PPP1R16B (98% identical), dog PPP1R16B (97% identical), guinea pig PPP1R16B (97% identical), mouse Ppp1r16b (96% identical), rat Ppp1r16b (96% identical), rabbit PPP1R16B (68% identical), tropical clawed frog ppp1r16b (54% identical), zebrafish ppp1r16b (45% identical), Drosophila melanogaster MYPT-75D (38% identical), Caenorhabditis elegans gfi-2 (32% identical). Paralogues in human: PPP1R16A (45% identical).
Diseases named in the same sentence as PPP1R16B in open-access papers:
PPP1R16B is named in the same sentence as 25 diseases in open-access papers, as found by Europe PMC text mining. Sharing a sentence is not in itself a finding about the gene and the disease. The quoted sentences say what the papers report.
lymphoma (3 papers, 2014 to 2025). A malignant (clonal) proliferation of B- lymphocytes or T- lymphocytes which involves the lymph nodes, bone marrow and/or extranodal sites. "In the case of Ppp1r16b, a previous study reported a modest increase in the expression of Ppp1r16b in several MLV-induced lymphomas." (PMID 35852337, 2022). "Notch1 has been widely described as one of the driver genes in T-cell acute lymphoblastic leukemia/lymphoma (T-ALL) (88, –, 90), while Ppp1r16b can promote aggressive lymphomas in mice." (PMID 35852337, 2022).
glioblastoma multiform (2 papers, 2023 to 2025). "The coding gene (ppp1r16b) for TIMAP was identified as a prognostic biomarker of glioblastoma multiforme, a type of primary brain tumor, shown by integrated analysis of methylation and expression profiles." (PMID 38139189, 2023).
Hyperglycemia (1 paper, 2023). An increased concentration of glucose in the blood. "PPP1R16B is involved in protein phosphatase binding, and its expression has been associated with pre-eclamptic human placentas and maternal hyperglycemia in mice." (PMID 37511531, 2023).
schizophrenia (1 paper, 2020). A major psychotic disorder characterized by abnormalities in the perception or expression of reality. "Furthermore, PPP1R16B has a central role in the integration of fast and slow neurotransmission in schizophrenia." (PMID 33374967, 2020).
tumor (5 papers, 2014 to 2025). "In the case of W390A MLV, mice 7, 11, and 12 had a dominant clone in the tumor with integrations into the Ppp1r16b, Pim1, and Notch1 oncogenes, respectively." (PMID 35852337, 2022). "CD48, SEPT1, ACAP1, PPP1R16B, and IL16 were all negatively correlated with tumor purity, supporting the results for highly correlating with ICILs." (PMID 31737562, 2019).
PPP1R16B also shares sentences with these, for which no sentence is quoted: cancer (3 papers); head and neck cancer (2); renal fibrosis (2); acute lymphoblastic leukemia (1); B-cell lymphoma (1); blood cancer (1); brain tumor (1); breast carcinoma (1); Burkitt lymphoma (1); diabetes mellitus (1); diffuse large B-cell lymphoma (1); gastric carcinoma (1); hematological malignancies (1); infection (1); neuroblastoma (1); Obesity (1); osteoporosis (1); prostate tumor (1); T-cell acute lymphoblastic leukemia (1); T-cell lymphoma (1).